Y_RNA (Y RNA )
Gene: Miscellaneous RNA gene on chromosome 4 (153,266,909 to 153,267,010, reverse strand). Ensembl gene ENSG00000201786.
Homologues: Orthologues: chimpanzee Y_RNA (100% identical), macaque Y_RNA (93% identical), pig Y_RNA (77% identical). Paralogues in human: Y_RNA (89% identical), Y_RNA (87% identical), RNY3 (86% identical), Y_RNA (86% identical), Y_RNA (85% identical), RNY3P16 (84% identical), Y_RNA (84% identical), RNY3P1 (83% identical), RNY3P14 (83% identical), Y_RNA (83% identical), RNY3P5 (82% identical), Y_RNA (82% identical), and 98 more.